COL1A2 (collagen type I alpha 2 chain)
Diseases named in the same sentence as COL1A2 in open-access papers (continued):
Sharing a sentence is not in itself a finding about the gene and the disease.
pancreatic cancer (14 papers, 2006 to 2025). "Importantly, collagen I produced by CAFs is built up as heterotrimers (encoded by COL1A1 and COL1A2), whereas pancreatic cancer cells produce COL1A1 homotrimers due to promoter hypermethylation of the COL1A2 gene." (PMID 37174079, 2023). "Moreover, COL1A2 is highly expressed in pancreatic cancer and represents a hallmark protein regulated by miR-25-3p." (PMID 35571032, 2022). "On the other hand, elevated mRNA levels of both COL1A1 and COL1A2 have been documented in colorectal, liver, ovarian, and pancreatic cancers, as well as in medulloblastoma." (PMID 41463322, 2025). "In addition, some researchers have reported that COL1A2 may be directly involved in pancreatic cancer proliferation, migration, and progression of the invasion." (PMID 36415513, 2022). "Furthermore, COL1A2 has been suggested to be a regulator of pancreatic cancer." (PMID 34283070, 2021). "COL1A1, COL1A2, ACTA2, PDGFRB and FAP displayed a significant positive correlation with this gene dataset in melanoma tumours (SKCM), whereas in pancreatic tumours (PAAD), that correlation was even stronger owing to their highly desmoplastic TME." (PMID 35654839, 2022). "We surveyed the coexpressed genes in the pancreatic cancer TCGA dataset and found that BMP1 was coexpressed with a large number of matrisome genes and especially collagen-related genes, such as COL1A1 and COL1A2." (PMID 33879793, 2021). "Data of COL1A2 expression in pancreatic cancer patients were not analyzed due to the lack of samples and the impossibility of reproducing replicates." (PMID 36834987, 2023). "Moreover, our study reveals the potential mechanism that hsa-miR-15a-5p regulates COL1A2, ITGA2, and LAMA3 so that monocytes and M1 macrophages are activated, which may have great effects on pancreatic cancer prognosis." (PMID 35899199, 2022).
glioblastoma (12 papers, 2009 to 2025). The most malignant astrocytic tumor (WHO grade IV). "The results of bioinformatics analysis, immunohistochemistry staining, and western blotting all revealed that the expression of COL1A2 was up-regulated in glioblastoma and related to poor prognosis outcomes in patients from public datasets." (PMID 37354488, 2023). "The expression levels of circ_COL1A2, circ_PTN, circ_VCAN, circ_PLOD2, circ_SMO, circ_CLIP2, circ_GLIS3, and circ_EPHB4 in glioblastoma (GBM) are significantly higher than those in normal tissues." (PMID 30064463, 2018). "Eight circRNAs, including circ_COL1A2, circ_PTN, circ_VCAN, circ_SMO, circ_PLOD2, circ_GLIS3, circ_EPHB4, and circ_CLIP2 showed significantly higher expression in glioblastoma (GBM) than in normal tissues." (PMID 28969099, 2017). "COL1A2 promotes the proliferation, migration, and invasion of glioblastoma cells." (PMID 37354488, 2023). "Finally, based on signaling pathways activated in patients with low levels of RND1, we identified an RND1low signature of six genes (MET, LAMC1, ITGA5, COL5A1, COL3A1, COL1A2) that is an independent prognostic factor in glioblastoma." (PMID 30333910, 2018). "The mechanism of tumor invasion and immune resistance involving COL6A3, COL1A1, COL1A2, LRRC15, IDO1, IL-6 and PTGS2 need to be further researched aiming to improve prognosis of aggressive glioblastoma." (PMID 33928021, 2021). "In glioblastoma, we identified an RND1low signature of six genes (ITGA5, COL3A1, COL5A1, MET, COL1A2, LAMC1), upregulated in glioblastoma patients with low RND1, that predicts the overall survival of glioblastoma patients." (PMID 31344837, 2019). "In addition, we also identified key genes, including MMP9, CD44, CDC42, COL1A1, COL1A2, CAMK2A, and CAMK2B, as potential target genes for diagnosing glioblastoma." (PMID 28191466, 2017). "For example, STCs exhibited, compared to STPs, the overexpression of several markers of the mesenchymal subtype of glioblastoma, such as COL1A1, COL1A2, COL5A1, IGFBP6, DCBLD2, many of which are also typically expressed by microglia or reactive astrocytes in glioblastoma microenvironment." (PMID 26188123, 2015).
hepatocellular carcinoma (12 papers, 2011 to 2025). A malignant tumor that arises from hepatocytes. "A vitro study actually showed that the down‐regulation of Col1a2 suppressed hepatocellular cancer, which supports that neighbor‐dependent genes are indeed associated with critical biological processes." (PMID 37815040, 2023). "COL1A2, a protein in the sub-network which is deregulated from cirrhosis, is involved in the development or progression of hepatoma." (PMID 21526182, 2011). "For instance, recent studies have identified miRNA binding site polymorphisms in genes implicated in migration, invasion, and angiogenesis, such as RASA1, COL1A2, CA9, CD147, VHL, and RYR3, which can influence susceptibility to hepatocellular carcinoma (HCC)." (PMID 41409896, 2025). "Moreover, COL1A2 is involved in the development or progression of hepatoma." (PMID 21526182, 2011).
Myocardial fibrosis (11 papers, 2017 to 2025). "Overexpression of COL1A1 and COL1A2 in the ECM–receptor interaction pathway led to myocardial fibrosis, as demonstrated in the CHF group of our experiment." (PMID 40785031, 2025). "Recent studies revealed that in DCM, circ_000203 exacerbated myocardial fibrosis by increasing Col1a2 and connective tissue growth factor (CTGF) via miR-26b-5p." (PMID 35034587, 2022). "The comparison between the T1DM and T2DM mice revealed an increase in myocardial fibrosis in the first group of animals, as confirmed with RT-PCR on freshly isolated CMs, in which the expressions of Col1a1, Col1a2 and Col3a1 were found to be higher in the T1DM mice compared to in the T2DM mice." (PMID 36674648, 2023). "The expression of different genes related to myocardial fibrosis was assessed in the rat hearts, revealing that at the 3rd week TiO2-NPs instillation the expression of different collagen isoform genes (namely COL1A2, COL3A1, COL4A1) were definitively upregulated in treated animals compared to CTRL." (PMID 31234877, 2019). "The expressional changes of these common target mRNAs could result in different diseases sharing common general pathomechanisms (e.g., NOX4 regulating oxidative stress in heart and kidney diseases, Col1a2 in myocardial fibrosis and tumor metastasis, BIM in different cancer types, etc.)." (PMID 29765562, 2018). "Consistently, Masson’s trichrome staining demonstrated a significant reduction in myocardial fibrosis after RDN, with lower expression of fibrosis-related genes including Col1a2, Timp1, Fn1 and α-SMA." (PMID 40958035, 2025). "The decline in cardiac function in HFpEF mice was also accompanied by a significant increase in the mRNA expression levels of Bnp and genes related to myocardial fibrosis, such as α-SMA, Fn1, Col1a2, and Timp1." (PMID 38402404, 2024). "Given that COL1A2, closely related to CCDC80, mediates the production of fibrillar collagen, we may assume that the combined action of CCDC80 and COL1A2 promotes myocardial fibrosis and accelerates the development of cardiomyopathy in the presence of obesity risk factors." (PMID 36547458, 2022).
colon cancer (10 papers, 2011 to 2023). "Based on the Spearman correlation coefficient, the top 30 genes most positively and negatively correlated with COL1A2 in colon cancer were identified with resulting figures displayed in the separate heatmaps." (PMID 37805556, 2023). "Taken together, the role of COL1A2 in colon cancer remains controversial and a comprehensive study regarding the expression, prognosis, and mechanism of COL1A2 in COAD is still absent." (PMID 37805556, 2023). "In colon cancer, the level of collagen expression is the key indicator to predicting the OS and risk, especially the types of COL1A1, COL1A2, COL3A1, COL4A3, and COL4A6." (PMID 36142424, 2022). "It further illustrates the close relationship between the gene (COL1A2) and the incidence of colon cancer." (PMID 34907282, 2021). "Taken together, NUDT21, GNB1, CLINT1, and COL1A2 were considered as core genes with a close relationship to colon cancer." (PMID 30881993, 2019). "Similarly, CDSE pretreatment induced COL1A1 and COL1A2 mRNA expression in fresh colonic tissues from colon cancer patients." (PMID 35840034, 2022). "Finally, NUDT21, GNB1, CLINT1, and COL1A2 core gene were selected due to their correlation with the prognosis of IIA stage colon cancer." (PMID 30881993, 2019). "In addition, COL1A1 and COL1A2 might forecast bad clinical results in gastric and colon cancer patient." (PMID 35646104, 2022). "However, a high expression of COL1A2 (HR 1.8, P = 0.017) was associated with worse overall survival for colon cancer patients, and there was no statistical significance in the other 78 hub genes." (PMID 30881993, 2019). "In the HCT116 human colon cancer cells, miR-4728-3p regulated the COL1A2 gene expression by targeting the wild type 3′untranslated region (3′UTR) of the COL1A2 gene in the focal adhesion pathway." (PMID 36057263, 2022). "And we found that NUDT21, GNB1, CLINT1, and COL1A2 might be the potential core genes that play an important role in the development and prognosis in IIA stage colon cancer." (PMID 30881993, 2019). "Finally, NUDT21, COL1A2, GNB1, and CLINT1 closely related to the overall survival of colon cancer were selected as core genes." (PMID 30881993, 2019). "In conclusion, this study showed that NUDT21, GNB1, CLINT1, and COL1A2 might be the potential core genes that play an important role in the development and prognosis in IIA stage colon cancer." (PMID 30881993, 2019). "this study suggested that NUDT21, GNB1, CLINT1, and COL1A2 might be the core genes for colon cancer that play an important role in the development and prognosis of IIA stage colon cancer." (PMID 30881993, 2019). "Moreover, further deeply investigated molecular mechanism of NUDT21, COL1A2, GNB1, CLINT1, and colon cancer is necessary; it is also the limitation of this study." (PMID 30881993, 2019).
lung carcinoma (10 papers, 2016 to 2024). "Moreover, in lung cancer, COL1A2 expression has been linked to tumor growth and metastasis." (PMID 38913913, 2024). "In lung cancer, increased COL1A2 expression has been correlated with poorer OS and advanced tumor stage." (PMID 38913913, 2024). "To further validate our RNA-Seq results, we utilized a different human lung cancer cell line H1838 and examined the expression level of COL1A2, LRP1, and HSP90B1, three representative genes up-regulated in our RNA-Seq analysis." (PMID 37487081, 2023). "So far, increasing numbers of studies have demonstrated that the expression of collagen family members, such as COL1A1 and COL1A2, was abnormal in several cancers, such as breast and lung cancers." (PMID 35426219, 2022). "Moreover, exogenous PGE2 has been shown to suppress TGF-β-induced fibronectin and type 1 collagen α2 (Col1A2) expression in human lung cancer A549 cells." (PMID 26875548, 2016). "Further in lung cancer groups, scRNA analysis showed higher expressing levels of COL1A1M COL1A2, PDGFRA and PDGFRB in identifying the CAF clusters specifically." (PMID 39034310, 2024). "In lung cancer stromal cells, FAP, COL1A1, and COL1A2 exhibited high sensitivity and specificity, reflecting the abundance of fibroblasts and CAFs." (PMID 39034310, 2024). "The markers of COL1A1, COL1A2, and FAP are significantly highly expressed in lung cancer, compared to normal tissues, while PDGFRA, PDGFRB, and ACTA2 either failed to be differentially expressed in cancer tissues, or were expressed in relative lower levels." (PMID 39034310, 2024). "COL1A2 did not distinguish the survival differences of overall, progression, and post-progression in the whole groups of lung cancer patients, However, it did actually accurately and efficiently in early staged lung adenocarcinoma." (PMID 39034310, 2024). "Analyzing the expression patterns of CAF markers in lung cancer tissues compared to normal tissues, we found that COL1A1, COL1A2, and FAP were significantly upregulated, indicating their potential as markers for identifying malignancies and metastatic diseases." (PMID 39034310, 2024). "Notably, the newly identified markers, COL1A1 and COL1A2, stand out as versatile tools for CAF identification, survival prognosis, and the evaluation of treatment responses in lung cancer patients." (PMID 39034310, 2024). "Further in lung cancer tissues, through scRNA analysis at “IMMUcan SingleCell RNAseq-Database” of lung cancer, for the first time, we proved the specificity of COL1A1, COL1A2, and FAP, all of three are highly enriched in subgroup of CAF, the cluster of which was circled." (PMID 39034310, 2024).
cardiac hypertrophy (9 papers, 2013 to 2024). "Since ADAR2 downregulation was associated with DCM we selected two cardiac hypertrophy and fibrosis associated genes (COL1A2 and IGF1) that are potential targets of miR-29b." (PMID 31039163, 2019). "For example, increased expression of Col1a1 and Col1a2, which encode for components of type I collagen, has been linked to remodeling of the cardiac matrix, and upregulation of collagen 1 is a well-established marker of cardiac fibrosis and is observed after cardiac hypertrophy." (PMID 35236346, 2022). "While both Col1a2+/− and Col1a2−/−mice are viable and grossly normal, Col1a2−/−mice uniquely developed progressive cardiac hypertrophy by 3 months of age." (PMID 37681905, 2023). "We also listed the differentially expressed proteins involved in cardiac hypertrophy, including glutaredoxin-3 (Glrx3) and collagen alpha-2(I) chain (Col1a2)." (PMID 23671862, 2013). "Here, we used constitutive and inducible models of Col1a2 deletion to investigate how the structure of type I collagen underlies ECM organization and content to support cardiac function, as well as how the expansion of type I collagen with disease/injury permits effective cardiac hypertrophy." (PMID 37681905, 2023). "Further evidence of the development of cardiac hypertrophy and cardiomyopathy in Mrps5cKO mice includes the upregulation of the hypertrophy and disease marker genes (Nppa, Nppb, and Myh7) and fibrosis marker genes (Col1a1, Col1a2, and Col1a3) in Mrps5cKO hearts." (PMID 36949106, 2023). "Two genes Col1A2 and IGF1 were selected based on their role in cardiac fibrosis and hypertrophy." (PMID 31039163, 2019).
dentinogenesis imperfecta (9 papers, 2012 to 2026). Dentinogenesis imperfecta (DGI) is a hereditary dentin defect characterized by abnormal dentin structure resulting in abnormal tooth development. "Dentinogenesis imperfecta is a common dental manifestation in OI, more frequently associated with COL1A2 mutations compared to COL1A1, due to the qualitative defects these mutations cause in collagen structure, a major component for bone and dentin." (PMID 40299462, 2025). "Supported by Pallos etal, documenting a family with dentinogenesis imperfecta associated with a minimal bone phenotype caused by a COL1A1 mutation, we conclude that the spontaneous COL1A2 mutation caused the proband’s dentin defects." (PMID 23227268, 2012). "Based on the clinical constellation of perinatal femoral deformity, dentinogenesis imperfecta, and absent blue sclerae, a diagnosis of OI, moderate form (Sillence type 4), COL1A2-related (OI type 4) was established." (PMID 42220822, 2026).
Obesity (9 papers, 2019 to 2025). Accumulation of substantial excess body fat. "Beyond their role in skeletal health, polymorphisms in the COL1A1 and COL1A2 genes have been implicated in the development of metabolic disorders such as obesity, type 2 diabetes mellitus (T2D), and cardiovascular disease." (PMID 40507792, 2025). "This study analyzed the associations of COL1A1 (rs1107946, rs1800012) and COL1A2 (rs42524) polymorphisms with BMD, obesity, and type 2 diabetes (T2D) in 554 postmenopausal women." (PMID 40507792, 2025). "Additionally, COL1A1 and COL1A2 have been identified as hub genes in obesity-induced cardiac fibrosis." (PMID 37662841, 2023). "NOX4, CCDC80, COL1A2, HTRA1, and KLHL29 were identified as key genes by LASSO regression analysis, among which HTRA1 and KLHL29 showed a close association with immune system infiltration in DCM and obesity." (PMID 36547458, 2022). "As an early model to assess obesity associated HFpEF development, mice on WD had no significant increase in nitrosative stress or cardiac fibrosis, two players in the pathogenesis of HFpEF, indicated by no changes in nos2 and col1a2 expression levels." (PMID 36844730, 2023). "The pioneering findings related to COL1A2 rs42524 and maternal fracture history, COL1A1 rs1107946 and obesity/T2D, and the age-dependent effects of COL1A1 rs1800012 on BMD underscore the importance of genetic factors in bone and metabolic health." (PMID 40507792, 2025). "The key genes, NOX4, CCDC80, COL1A2, HTRA1, and KLHL29 were significantly expressed in DCM, with KLHL29 and HTRA1 especially closely associated with the immune response, which might be markers for obesity-induced DCM and be potential avenues for exploration in immunotherapy." (PMID 36547458, 2022). "Obesity participates in cardiac fibrosis by up-regulating the expression of COL1A1 and COL1A2 in cardiac fibroblasts and further significantly increasing myocardial collagen content." (PMID 36547458, 2022).
osteoarthritis (9 papers, 2016 to 2025). A noninflammatory degenerative joint disease occurring chiefly in older persons, characterized by degeneration of the articular cartilage, hypertrophy of bone at the margins and changes in the synovial membrane. "One study found increased mRNA expression in collagen type I chains, Col1a1 and Col1a2, in the hip samples of osteoarthritis patients compared to control non-osteoarthritis samples." (PMID 40647239, 2025). "They reported a twofold increase in the mRNA ratio of Col1a1/Col1a2 in osteoarthritis bone in comparison to the control." (PMID 40647239, 2025). "This study aimed to elucidate the roles of microRNA (miR)-4738-3p and the collagen type I alpha 2 chain (COL1A2) gene in the pathogenesis of osteoarthritis (OA) through bioinformatics analysis and cellular assays." (PMID 38059912, 2024). "The analysis revealed a notable upregulation of key osteoarthritis markers, such as COL10A1, MMP13, and SPP1, along with downregulating chondrogenic markers, including ACAN, COL1A2, COL2A1, and SOX9." (PMID 39337501, 2024). "The results demonstrated that miR-92a was downregulated in equine synovial fluid from horses with severe osteoarthritis and there was a significant increase in COMP, COL1A2, RUNX2 and SOX9 following miR-92a mimic treatment of equine chondrocytes in monolayer culture." (PMID 36555166, 2022). "Thus, lnc-SAMD14-4 may play a key role in the pathogenesis of osteoarthritis by promoting the expression of the COL1A1 and COL1A2 genes." (PMID 31534838, 2019).
prostate carcinoma (9 papers, 1997 to 2024). A carcinoma that arises from epithelial cells of the prostate gland. "We further confirmed that Cxcl5 was downregulated, and Cxcl9/10 were upregulated in the FACS-isolated stromal cells from both RM-1 xenografts and prostate cancer tissues of Col1a2-Foxf2-TRAMP mice as compared to their respective controls." (PMID 36369237, 2022). "Median adjusted scores of the control and Col1a2-Foxf2-TRAMP mouse prostate cancers were 30 and 22, respectively and were statistically different, supporting a delayed disease progression in the Col1a2-Foxf2-TRAMP group." (PMID 36369237, 2022). "Additionally, while CDC20, COL1A2 and S100A10 possess recognized pro-oncogenic activities, the precise roles of B4GALNT4 and NUAK1 in prostate cancer warrant elucidation." (PMID 39391236, 2024). "In addition, berberine inhibited prostate cancer cell invasion and migration by downregulating several EMT-related genes, such as platelet-derived growth factor receptor-beta (PDGFRB), collagen, type I, alpha 2 (COL1A2), and bone morphogenetic protein 7 (BMP7)." (PMID 35889396, 2022).